LRCH4 (leucine rich repeats and calponin homology domain containing 4)
Description:
Accessory protein that regulates signaling by multiple TLRs, acting as a broad-spanning regulator of the innate immune response. In macrophages, binds LPS and promotes proper docking of LPS in lipid raft membrane. May be required for lipid raft maintenance.
Synonyms: LRN; LRRN1; LRRN4; PP14183
Tractability: Antibody: UniProt places it where antibodies can reach, with medium confidence; UniProt predicts a signal peptide or a membrane-spanning region; its Gene Ontology location is reachable by antibodies, with medium confidence. PROTAC: ubiquitination databases record sites on it; its protein half-life has been measured.
Gene: Protein-coding gene on chromosome 7 (100,574,011 to 100,586,161, reverse strand). Ensembl gene ENSG00000077454.
Subcellular location: Cell membrane
Subcellular location (Human Protein Atlas): Cytosol; Focal adhesion sites; Nucleoplasm
Gene Ontology:
Molecular function: protein binding
Biological process: membrane raft assembly; nervous system development; positive regulation of toll-like receptor signaling pathway
Cellular component: PML body; plasma membrane
Genetic constraint (gnomAD): Loss-of-function variants: 56 observed, 80.14 expected, observed/expected ratio (o/e) 0.7, 90% interval 0.56 to 0.87. The upper end of that interval is the gene's LOEUF score, 0.87, which puts it in group 3 of 6, group 1 being the genes least tolerant of losing a copy. Missense variants: 895 observed, 923.98 expected, observed/expected ratio (o/e) 0.97, 90% interval 0.92 to 1.02. Synonymous variants: 442 observed, 415.08 expected, observed/expected ratio (o/e) 1.06, 90% interval 0.98 to 1.15.
Homologues: Orthologues: chimpanzee LRCH4 (99% identical), rabbit LRCH4 (91% identical), pig LRCH4 (91% identical), macaque LRCH4 (89% identical), dog LRCH4 (89% identical), guinea pig LRCH4 (88% identical), rat Lrch4 (84% identical), mouse Lrch4 (79% identical). Paralogues in human: LRCH3 (45% identical), LRCH1 (40% identical), LRCH2 (37% identical), LRRK1 (25% identical), SCRIB (21% identical), ERBIN (18% identical), LRRC7 (17% identical), PHLPP1 (17% identical), PHLPP2 (15% identical), PIDD1 (15% identical), MFHAS1 (15% identical), LRRC28 (13% identical), and 19 more.
Diseases named in the same sentence as LRCH4 in open-access papers:
LRCH4 is named in the same sentence as 7 diseases in open-access papers, as found by Europe PMC text mining. Sharing a sentence is not in itself a finding about the gene and the disease. The quoted sentences say what the papers report.
acute myeloid leukemia (1 paper, 2020). Acute myeloid leukemia (AML) is a group of neoplasms arising from precursor cells committed to the myeloid cell-line differentiation. "In patients with acute myeloid leukemia, divided into low and high LRCH4 expression groups, higher LRCH4 expression is linked to decreased mortality." (PMID 33072765, 2020).
asthma (1 paper, 2022). "Two proteins were regulated by the disease status; leucine-rich repeats and calponin homology domain-containing 4 (Lrch4) and microtubule-associated serine/threonine-protein kinase 4 (MAST4) were upregulated during asthma exacerbation." (PMID 36359743, 2022). "The diagnostic potential of Lrch4 and MAST4 as biomarkers and the involvement of these proteins in asthma pathophysiology require further investigation." (PMID 36359743, 2022).
colorectal cancer (1 paper, 2020). A primary or metastatic malignant neoplasm that affects the colon or rectum. "In colorectal cancer, a potential complication of ulcerative colitis, expression of LRCH3 is increased compared to colorectal tissues of healthy individuals and expression of LRCH4 is increased in colorectal cancer patient samples with more advanced stages of cancer." (PMID 33072765, 2020).
Hypertension (1 paper, 2026). The presence of chronic increased pressure in the systemic arterial system. "By applying this novel approach, we not only confirmed well-established biomarkers for diseases such as hypertension (UBE2L6) and leukemia (LRCH4) but also identified novel protein candidates." (PMID 41724807, 2026).
LRCH4 also shares sentences with these, for which no sentence is quoted: bacterial infection (1 paper); cancer (1); leukemia (1).